PCSK9 (proprotein convertase subtilisin/kexin type 9)
Diseases named in the same sentence as PCSK9 in open-access papers (continued):
Sharing a sentence is not in itself a finding about the gene and the disease.
Hypercholesterolemia (continued). "While PCSK9 became one of the most promising targets for the improvement of hypercholesterolemia, as for its inhibitors constituted a new class of lipid-lowering drugs, whether PCSK9 participates in regulating T synthesis remains unknown." (PMID 37935689, 2023). "Indeed, according to the European Atherosclerosis Society (EAS) Familial Hypercholesterolemia Studies Collaboration (FHSC) global registry, use of PCSK9 inhibitors among patients with HeFH was associated with greater odds of having LDL-C lower than 1.8 mmol/L." (PMID 36855099, 2023). "PCSK9 was clearly associated with inflammation and hypercholesterolemia, but did not predict mortality at one year." (PMID 37620933, 2023). "PCSK9 inhibitors are effective treatments for hypercholesterolemia." (PMID 37958806, 2023). "Clinical studies have noted elevated concentrations of PCSK9 in patients with hypercholesterolemia." (PMID 37892538, 2023). "Of concern, in a 2021 trial, two young patients with pure-sibling familial hypercholesterolemia (12 years old and 16 years old) experienced almost complete regression of plaque after intensive lipid-lowering with PCSK9 inhibitors in combination with other lipid-lowering agents." (PMID 38273837, 2023). "Notably, individual responses to the PCSK9 inhibitor evolocumab vary widely among patients with homozygous familial hypercholesterolemia (HoFH)." (PMID 38093957, 2023). "In case of extreme risk (previous cardiovascular events or multi-vessel disease, familial hypercholesterolemia), starting therapy straight away with statins, ezetimibe and a PCSK9 inhibitor may be considered." (PMID 37623342, 2023). "Therefore, PCSK9 was accounted as the third gene responsible of familial hypercholesterolemia that required further bimolecular research to fully understand its association with LDL receptors." (PMID 36935878, 2023). "PCSK9 inhibitor used in treatment of familial hypercholesterolemia." (PMID 38125244, 2023). "Notably, several clinical studies have demonstrated the antiplatelet effects of PCSK9 in patients with hypercholesterolemia and found it to be an effective and safe strategy for treating patients with uncontrolled hyperlipidemia and coronary artery disease." (PMID 35207479, 2022). "Consequently, the PCSK9 inhibitors alirocumab and evolocumab have been developed and are currently used to treat severe hypercholesterolemia patients." (PMID 36430776, 2022). "The importance of PCSK9 for LDL-c homeostasis was further highlighted when it was discovered that PCSK9 loss- and gain-of-function mutations cause hypo- or hypercholesterolemia in patients with devastating risks for atherosclerotic cardiovascular disease and its progression." (PMID 36005422, 2022). "Thus, we suggest that allicin, capsaicin, and other natural PCSK9 inhibitors be used as cholesterol-lowering agents in hypercholesterolemia subjects or added to statin therapy or other lipid-lowering therapies." (PMID 36430776, 2022).
Hypercholesterolemia (continued). "In this review, we evaluated several studies in the literature to analyze the benefits and deleterious effects of the use of monoclonal antibodies (MABs)-based proprotein convertase subtilisin-kexin type 9 (PCSK9) inhibitors in patients with hypercholesterolemia." (PMID 35795514, 2022). "Taken together, cell and animal models and patient cohorts relevant for chronic liver diseases and treated with pharmacological PCSK9 inhibitors have revealed multiple layers of additional PCSK9 functions that extend well beyond its therapeutic aspect in overcoming hypercholesterolemia." (PMID 35162992, 2022). "Their findings suggest PCSK9 as a therapeutic target for siRNA intervention and offer a treatment strategy for lipid-lowering therapy that can be used to treat cardiovascular disease patients with hypercholesterolemia." (PMID 36005422, 2022). "Indeed, PCSK9 inhibition is considered an attractive target for therapy against hypercholesterolemia." (PMID 36555447, 2022). "Although PCSK9 inhibitor antibodies represent a recent avenue of combination treatment with statins and ezetimibe for hypercholesterolemia in patients with treatment-resistant LDL-C levels and/or a history of statin intolerance, their clinical benefits in these patients appear to be very promising." (PMID 35795514, 2022). "Nevertheless, a small-molecule inhibitor of PCSK9 is highly valued as a treatment option for hypercholesterolemia given its capacity to provide a cost-competitive alternative to anti-PCSK9 monoclonal antibodies, coupled with the potential for ease of oral administration." (PMID 36209894, 2022). "This means that hypercholesterolaemia treatment can be based on suppressing the PCSK9." (PMID 36289901, 2022). "Many hypercholesterolemia patients possess a high level of PCSK9." (PMID 36267835, 2022). "A study named Open-Label Study of Long Term Evaluation Against LDL-C (OSLER-1) was carried out to assess the long-term impact of evolocumab in an open-label hypercholesterolemia treatment for a duration of five years - the longest period for the use of PCSK9 inhibitor antibodies." (PMID 35795514, 2022). "A large number of clinical trials have investigated the lipid-lowering effect and clinical benefit of mAbs to PCSK9 in many categories of patients with hypercholesterolaemia or established atherosclerotic cardiovascular disease (ASCVD), proving their efficacy and safety." (PMID 35877035, 2022). "In patients with hypercholesterolemia who received background statin and acetyl salicylic acid therapy, platelet function parameters were significantly reduced after 12 months of treatment with the monoclonal antibody (mAb) anti-PCSK9 alirocumab or evolocumab." (PMID 36324757, 2022). "For example, proprotein convertase subtilisin/kexin type 9 serine protease (PCSK9) inhibitors, a newer class of drugs used to treat hypercholesterolaemia, have also been shown to lower the levels of circulating ceramides and other sphingolipids, and can be safely combined with statins." (PMID 36230715, 2022). "In addition, fitusiran and inclisiran target the antithrombin gene and PCSK9 gene for the treatment of hemophilia and hypercholesterolemia, respectively." (PMID 35200353, 2022). "Still, concerns remain regarding whether base editing of PCSK9 is a safe method for the treatment of hypercholesterolemia." (PMID 35900635, 2022). "Our study suggests that therapy with PCSK9 inhibitors may be justified even in cases of mild hypercholesterolemia, especially if this treatment is used in patients with high cardiovascular risk." (PMID 35566668, 2022). "This study aimed to investigate whether PCSK9 inhibitors had any effect on the markers of coagulation and fibrinolysis in subjects with primary isolated hypercholesterolemia." (PMID 35566668, 2022).
Hypercholesterolemia (continued). "The mouse group in which hypercholesterolemia evoked by PCSK9 expression and HFD (HCi, single hit) was combined with induction of chronic hyperglycemia using STZ injection (double hit) is hereafter termed HGHCi (high glucose high cholesterol–inducible) throughout the manuscript." (PMID 35350534, 2022). "By examining the three novel variants of PCSK9 two of them (Gly59Arg, Ala68Asp) occurring in the pro-domain in the same individual, a 25- year-old male classified as ‘possible’ FH, with LDL-C levels of 6 mmol/L and self-reported hypercholesterolemia." (PMID 36329474, 2022). "However, few head-to-head studies evaluated the efficacy on the lowering in other atherogenic apolipoproteins and safety of PCSK9 inhibitors at different dosages as an add-on statins therapy in hypercholesterolemia patients." (PMID 35444537, 2022). "Since PCSK9 and Lp(a) levels are two predictors of coronary artery calcification in asymptomatic patients with familial hypercholesterolemia, future studies are needed to further elucidate the role of Lp(a) and PCSK9 in cardiovascular disease in Middle Eastern populations." (PMID 35893257, 2022). "Moreover, carotid intima-media thickness was reduced by treatment with PCSK9-antibodies in addition to ongoing lipoprotein apheresis in only 14 heterozygous familial hypercholesterolemia patients." (PMID 35052831, 2022). "Currently, PCSK9 inhibitors are used to treat patients with familial hypercholesterolemia." (PMID 36362216, 2022). "If conventional drug therapy fails in patients with severe familial hypercholesterolemia, PCSK9 inhibitor therapy should be administered; if these agents are not available, performing selective LDL apheresis could be considered." (PMID 35628997, 2022). "The probability of patients with familial hypercholesterolemia developing into T2DM is much lower than their unaffected relatives, which indirectly means that PCSK9-GOF variants might be associated with NOD." (PMID 35571202, 2022). "Therefore, two strategies among others were suggested against hypercholesterolemia: inhibition of intracellular cholesterol biosynthesis by statins and a variety of anti-PCSK9 therapeutic modalities." (PMID 35657919, 2022). "However, there is limited evidence for PCSK9 monoclonal antibody in homozygous familial hypercholesterolemia (HoFH), so only evolocumab has been labeled for this indication." (PMID 36230934, 2022). "Thus, PCSK9 represents an important pharmacological target for controlling hypercholesterolemia and its inhibition with mAbs seems the most effective approach for reducing CV risk." (PMID 33690097, 2021). "In this respect, new observations have likened PCSK9 expression in the cortical collecting ducts of primary glomerulonephritis patients to hypercholesterolemia, proposing the kidney, as a source of PCSK9, as a first-line therapeutic target for dyslipidemia in this population." (PMID 34822418, 2021). "Moreover, a recent experimental study in a LDL-R+/- mouse model investigated the potential effect of a vaccine targeting PCSK9 (PCSK9Qβ-003) on hypercholesterolemia and kidney fibrosis." (PMID 34336112, 2021). "Therefore, inhibiting PCSK9 along with statin therapies has become an important and attractive addition in managing hypercholesterolaemia." (PMID 34356856, 2021). "Combined, these genetic findings suggested that inhibition of PCSK9 could be a novel and safe target to treat hypercholesterolemia." (PMID 34731223, 2021).
Hypercholesterolemia (continued). "The findings concluded that A. planci contained promising PCSK9 small molecule inhibitors that have vast potential to be developed as therapeutic agents against hypercholesterolemia which in turn, will reduce the progression or prevent the development of atherosclerosis and cardiovascular diseases." (PMID 34443682, 2021). "For hypercholesterolemia, the small synthetic molecule bempedoic acid has the added benefit of selective liver activation, whereas inclisiran, a hepatic inhibitor of the PCSK9 synthesis, has comparable effects with PCSK9 monoclonal antibodies." (PMID 33694108, 2021). "Targeting PCSK9 is a promising, but costly approach, to treat hypercholesterolemia." (PMID 33461570, 2021). "Therefore, the use of PCSK9 inhibitors, especially in patients with hypercholesterolemia, should reduce this adverse effect and improve the antiviral efficiency of the organism related to INF-β." (PMID 34689776, 2021). "Injectable PCSK9 monoclonal antibody or siRNA is currently used in clinics worldwide to treat hypercholesterolemia and could be combined with current therapies in cancer/metastasis." (PMID 34606887, 2021). "And PCSK9 inhibition can be used for treatment of hypercholesterolemia." (PMID 34504788, 2021). "Inclisiran (a small interference RNA) and statin administration in patients with atherosclerotic cardiovascular disease or heterozygous hypercholesterolemia patients reduced PCSK9 levels in blood and LDL-cholesterol levels in ORION-9 and ORION-10/ORION-11 phase 3 clinical trials." (PMID 33834043, 2021). "A limited number of studies have so far explored whether PCSK9 shows any sex-specific differences in conditions like myocardial infarction, or hypercholesterolemia." (PMID 33692700, 2021). "Furthermore, for patients requiring additional reduction of LDL-C, such as in atherosclerotic cardiovascular disease or familial hypercholesterolemia, PCSK9 inhibitors have been approved." (PMID 34860135, 2021). "In addition, PCSK9 inhibitors determine an improvement in endothelial function in patients with familial hypercholesterolemia, an iconic population for premature cardiovascular disease." (PMID 33916362, 2021). "Early safety studies of the PCSK9 inhibitors evolocumab and alirocumab, used to treat hypercholesterolemia, hinted that PCSK9 inhibition may negatively impact cognition but more recent, longer-term clinical trials found no adverse neurocognitive events." (PMID 32595449, 2020).
Hypercholesterolemia (continued). "Recently it was found that FGF21 serves as a potential negative regulator of PCSK9, which is in line with our observation that hypermethylation of PCSK9 corresponds with higher circulating FGF21 levels in patients with hypercholesterolemia compared to control subjects." (PMID 33028190, 2020). "Collectively, these data identified PCSK9 as a key player in hypercholesterolemia." (PMID 33364976, 2020). "Further prospective studies in a larger number of patients with polygenic hypercholesterolemia and monogenic FH would provide more information and evaluate the LDL-C response to oral lipid-lowering medications and PCSK-9 inhibitors, and to assess their CV risk." (PMID 32443900, 2020). "The sensitivity of PCSK9 in predicting hypercholesterolemia was 0.73, and the specificity was 0.69." (PMID 32349585, 2020). "Furthermore, we found that when PCSK9 was >255.05 ng/ml, NS patients were more prone to develop hypercholesterolemia." (PMID 32349585, 2020). "If any of these proteins results to be the endogenous inhibitor of PCSK9’s function, its identification could help in the design of more efficient drugs/biologicals to treat hypercholesterolemia." (PMID 32587953, 2020). "Recent studies found that elevated hepatic IDOL and PCSK9 may contribute to NS-induced hypercholesterolemia, and ablation of hepatic PCSK9 attenuated NS-induced hypercholesterolemia in mice." (PMID 32437440, 2020). "By mediating the degradation of LDL-R, elevated plasma PCSK9 may play a major role in the pathogenesis of hypercholesterolemia in PNS patients." (PMID 32349585, 2020). "Hence, gain of function and loss of function mutations in PCSK9 have been found to modulate serum cholesterol levels in humans making PCSK9 inhibitors an attractive target to treat hypercholesterolemia in humans." (PMID 32244519, 2020). "The area under the receiver operating characteristic (ROC) curve (AUC) for the prediction of hypercholesterolemia in NS patients using plasma PCSK9 was 0.71 (95% CI 0.58–0.84, p = 0.007), the Youden index was 0.42, and the corresponding PCSK9 value was 267.60 ng/ml." (PMID 32349585, 2020). "Aggressive lipid-lowering drugs such as proprotein convertase subtilisin/kexin type 9 (PCSK9) inhibitors have been shown to reduce carotid artery plaque burden, total cholesterol, and low-density lipoprotein-c in patients with heterozygous familial hypercholesterolemia (FH)." (PMID 33094041, 2020).